CTTNBP2 (cortactin binding protein 2)
Description:
Regulates the dendritic spine distribution of CTTN/cortactin in hippocampal neurons, and thus controls dendritic spinogenesis and dendritic spine maintenance. Associates with the striatin-interacting phosphatase and kinase (STRIPAK) core complex to regulate dendritic spine distribution of the STRIPAK complex in hippocampal neurons.
Synonyms: CortBP2; C7orf8; KIAA1758; Orf4
Tractability: PROTAC: its protein half-life has been measured.
Gene: Protein-coding gene on chromosome 7 (117,710,651 to 117,874,139, reverse strand). Ensembl gene ENSG00000077063.
Subcellular location: Cytoplasm, cell cortex; Cell projection, dendritic spine
Subcellular location (Human Protein Atlas): Midbody ring; Cytosol
Gene Ontology:
Molecular function: protein binding; SH3 domain binding
Biological process: regulation of synapse organization; regulation of modification of postsynaptic actin cytoskeleton
Cellular component: dendritic spine; FAR/SIN/STRIPAK complex; glutamatergic synapse; cell cortex; postsynaptic actin cytoskeleton; synaptic vesicle
Genetic constraint (gnomAD): Loss-of-function variants: 78 observed, 121.61 expected, observed/expected ratio (o/e) 0.64, 90% interval 0.53 to 0.77. The upper end of that interval is the gene's LOEUF score, 0.77, which puts it in group 3 of 6, group 1 being the genes least tolerant of losing a copy. Missense variants: 1,652 observed, 1,834.6 expected, observed/expected ratio (o/e) 0.9, 90% interval 0.86 to 0.94. Synonymous variants: 676 observed, 685.39 expected, observed/expected ratio (o/e) 0.99, 90% interval 0.93 to 1.05.
Homologues: Orthologues: chimpanzee CTTNBP2 (99% identical), macaque CTTNBP2 (98% identical), pig CTTNBP2 (89% identical), rabbit CTTNBP2 (87% identical), guinea pig CTTNBP2 (86% identical), mouse Cttnbp2 (85% identical), rat Cttnbp2 (85% identical), tropical clawed frog cttnbp2 (59% identical), zebrafish cttnbp2 (46% identical). Paralogues in human: TANC2 (15% identical), TANC1 (13% identical), ANKRD65 (6% identical), ANKRD63 (4% identical).
Diseases named in the same sentence as CTTNBP2 in open-access papers:
CTTNBP2 is named in the same sentence as 34 diseases in open-access papers, as found by Europe PMC text mining. Sharing a sentence is not in itself a finding about the gene and the disease. The quoted sentences say what the papers report.
autism (10 papers, 2013 to 2025). Persistent deficits in social interaction and communication and interaction as well as a markedly restricted repertoire of activity and interest as well as repetitive patterns of behavior. "Meanwhile, CTTNBP2 knockout mice have reduced brain zinc levels – a risk factor for autism – and altered synaptic protein targeting, while zinc supplementation rescues synaptic retention of CTTNBP2 and improves social behaviors in these mice." (PMID 38438384, 2024). "We identified a rare de novo missense mutation, p.M115T, in the CTTNBP2 gene in patients affected by autism." (PMID 36670631, 2022). "Gene modification studies at the cellular level and in animal models have linked ASD-associated mutations in CTTNBP2 to altered neuronal function and the production of autism-like behaviors." (PMID 36670631, 2022). "In conclusion, although the present study is currently insufficient to confirm that the de novo mutation M115T in CTTNBP2 directly causes the autism phenotype, our study provides support for the assertion that CTTNBP2 is a strong candidate gene in autism." (PMID 36670631, 2022). "This study reports that autism-linked mutations of CTTNBP2 regulate phase separation to control synaptic enrichment of that protein." (PMID 35562389, 2022). "Moreover, it has been identified as a significant candidate gene in autism-spectrum disorders, with autism-linked mutations in CTTNBP2 leading to a reduction in dendritic spine density through various mechanisms." (PMID 39843641, 2025). "Although the present study is currently insufficient to support the assertion that the de novo mutation M115T in CTTNBP2 directly causes the autism phenotype, our study provides support for the assertion that this mutation is a candidate clinically relevant variant in autism." (PMID 36670631, 2022). "However, how ASD-linked mutations of CTTNBP2 alter neuronal function to result in autism-like symptoms remains elusive." (PMID 33168105, 2020). "For example, CTTNBP2 is an autism-related gene mainly expressed in neurons and highly enriched in the dendritic spine." (PMID 36979179, 2023). "The CTTNBP2 gene is located on chromosome 7q31, a candidate region for autism." (PMID 36670631, 2022). "CTTNBP2 is located in a region associated with ASD, namely, the autism candidate region at 7q31." (PMID 36670631, 2022). "The CTTNBP2 gene is a known strong autism candidate gene in the SFARI database." (PMID 36670631, 2022). "The contribution of CTTNBP2 to dendritic spine formation indicates that CTTNBP2 might participate in controlling cognitive functions related to autism or other psychiatric disorders." (PMID 23527149, 2013).
autism spectrum disorder (7 papers, 2016 to 2025). A spectrum of developmental disorders that includes autism, and Asperger syndrome. "CTTNBP2 is a candidate gene for autism spectrum disorder and mice with autism spectrum disorder-linked mutations in CTTNBP2 knocked in have impaired synaptic function." (PMID 38438384, 2024). "Genomic analyses of patients with autism spectrum disorders (ASDs) indicated that both CTTNBP2 and syndecan-2 were associated with ASDs." (PMID 26819769, 2016). "For instance, human CTTNBP2 (1663 amino acid residues) is a neuron-specific F-actin-associated SCD protein that is involved in the formation and maintenance of dendritic spines and it is associated with autism spectrum disorders." (PMID 38393970, 2024). "In contrast to KLHL17/AF, CTTNBP2 mainly regulates the density of dendritic spines, though some severe deficits identified from patients with autism spectrum disorders or due to complete knockout may also result in reduced spine width and length." (PMID 33256713, 2020).
glioma (2 papers, 2008 to 2023). A benign or malignant brain and spinal cord tumor that arises from glial cells (astrocytes, oligodendrocytes, ependymal cells). "Moreover, TTBK2, NAV1, and CTTNBP2 were protective factors for glioma, while SRCIN1, TRIO, KIF18A, and SLAIN2 were risk factors." (PMID 36979179, 2023). "TTBK2, NAV1, and CTTNBP2 were considered as protective factors, while SRCIN1, TRIO, KIF18A, and SLAIN2 were risk factors for glioma." (PMID 36979179, 2023). "This confirmed that gliomas with 1p19q codeletion overexpressed neuronal/normal brain genes (AKR1C3, C20orf42, CTTNBP2, L1CAM, GALNT13) as well as genes implicated in gliogenesis and neurogenesis (OLIG2, BMP2, NOG, DCX, ATOH8)." (PMID 18492260, 2008). "Our study found that compared with normal tissues, CTTNBP2, KIF18A, NAV1, SLAIN2, and TRIO were upregulated in glioma, while SRCIN1 and TTBK2 were downregulated." (PMID 36979179, 2023). "Compared with the normal samples, except for SLAIN2, the CTTNBP2, KIF18A, NAV1, and TRIO protein expression in glioma was elevated, while SRCIN1 and TTBK2 were decreased." (PMID 36979179, 2023).
mental disorder (2 papers, 2013 to 2022). A disease that has its basis in the disruption of mental process. "Eight genes are implicated in viral (SEC14L1, JMJD6, SRSF2, TMPRSS2, MX1, MX2) or bacterial (COL8A1, SPIRE1) infections, seven genes (MFSD11, METTL23, CTTNBP2, BACE2, IMPA2, MPPE1 and GNAL) are involved in mental disorders and one gene (MGAT5B) is related to the Golgi complex." (PMID 35581286, 2022).
neuroblastoma (2 papers, 2017 to 2025). Neuroblastoma (NB) is the most common solid, extracranial childhood tumor. "CTTNBP2 (synapse maintenance) and REEP3 (vesicle trafficking) are enriched for regulatory variants, of which at least six (35%) alter transcription factor-DNA binding in neuroblastoma cells." (PMID 29042551, 2017).
Anxiety (1 paper, 2020). Intense feelings of nervousness, tension, or panic often arise in response to interpersonal stresses. "However, Cttnbp2+/−, R533* and M120I mutant mice did not display any noticeable phenotype in terms of locomotion or anxiety." (PMID 33168105, 2020).
asthma (1 paper, 2025). "Adult asthma subjects in the extreme temperature fluctuation group showed consistently decreased Wfdc21, Cib3, Gpr171, and Cttnbp2 expression, while increased Tiam2 and Cma1 expression." (PMID 40313552, 2025). "We observed that extreme low temperature decreased Wfdc21, Cttnbp2, Cib3, and Cma1 expression in mild and moderate asthma, while increased expression in severe asthma." (PMID 40313552, 2025). "Extreme low temperature decreased Wfdc21, Cttnbp2, Cib3, and Cma1 expression in mild and moderate asthma, while increased expression in severe asthma." (PMID 40313552, 2025). "Further, extreme temperature fluctuations consistently led to decreased expression of Wfdc21, Cib3, Gpr171, and Cttnbp2 in mice and asthma patients." (PMID 40313552, 2025). "Extreme temperature decreased Wfdc21, Cttnbp2, Cib3, and Cma1 expression in mild and moderate asthma, while increased expression in severe asthma patients." (PMID 40313552, 2025). "In addition, asthma subjects in the extreme temperature fluctuation group showed decreased expression of Wfdc21, Cib3, Gpr171, and Cttnbp2, while Tiam2 and Cma1 expression increased." (PMID 40313552, 2025).
depression (1 paper, 2024). "Two SNPs (rs6424532 [LOC105378800], and rs2402273 [LSM8/CTTNBP2]) had a marginally significant indirect effect on broad depression through log of pack-years among males (p = 4.0 × 10−3 and p = 4.1 × 10−3, respectively)." (PMID 38790194, 2024). "In addition, rs263575 [BNC2/CNTLN] had a marginally significant indirect effect on broad depression among females but not males, and rs2402273 [LSM8/CTTNBP2] had a marginally significant indirect effect on broad depression among males but not females." (PMID 38790194, 2024).
glaucoma (1 paper, 2025). Increased pressure in the eyeball due to obstruction of the outflow of aqueous humor. "CTTNBP2 has been identified as being associated with glaucoma through GWASs, and our research reveals its highly specific expression in TM cells, potentially linking it to microtubule dynamics, which may adapt to dynamic aqueous humor outflow and fluctuating IOP." (PMID 40136401, 2025).
ovarian carcinoma (1 paper, 2021). A malignant neoplasm originating from the surface ovarian epithelium. "Moreover, in ovarian cancer, HEIH facilitated cell progression and blocked cell senescence by regulating miR-3619-5p and CTTNBP2." (PMID 34760016, 2021).
prostate carcinoma (1 paper, 2019). A carcinoma that arises from epithelial cells of the prostate gland. "Using a multicolor fluorescence in situ hybridization approach, the copy number alterations of six genes known to be involved in aggressive prostate cancer (PTEN, MYC, MEN1, PDGFB, CTTNBP2, and TBL1XR1) was explored in a group of recurrent and in a group of nonrecurrent prostate cancer patients." (PMID 31366128, 2019).
Zinc deficiency (1 paper, 2022). A deficiency of the essential metal Zinc; an essential cofactor for many enzymes. "However, all ASD-linked CTTNBP2 mutant variants still responded to zinc, providing a potential explanation for how zinc supplementation ameliorates the neuronal and brain defects caused by Cttnbp2 deficiency and is consistent with a role for zinc deficiency in ASD etiology." (PMID 35562389, 2022).
cancer (4 papers, 2014 to 2025). A tumor composed of atypical neoplastic, often pleomorphic cells that invade other tissues. "Since the proposed mechanism of CTTNBP2 CRE SNV1 was to decrease a binding for a transcriptional activator, among the TFs reported by motifbreakR tool, we selected STAT3 because of its well-known role in several cancers." (PMID 39843641, 2025).
neurological disorders (3 papers, 2013 to 2022). "Weaver is a neurological disease and while NRCAM, PNPLA8, and CTTNBP2 are all expressed in nervous tissues, overall NRCAM is expressed at higher levels across all nervous tissues, including the spinal cord." (PMID 23527149, 2013). "Indeed, identified genes are implicated in viral (SEC14L1, JMJD6, SRSF2, TMPRSS2, MX1, MX2) bacterial (COL8A1, SPIRE1), and neurological disorders (MFSD11, METTL23, CTTNBP2, BACE2, IMPA2, MPPE1 and GNAL), or in the functions of the Golgi complex (MGAT5B), organelle where viral envelope is occurred." (PMID 35581286, 2022).
tumor (3 papers, 2021 to 2025). "In summary, the CTTNBP2 CRE SNV1 variant leads to reduced expression of CTTNBP2 which appears to enhance the tumorigenic phenotype in HEK-293 cells, indicating a potential role for CTTNBP2 as a novel tumor suppressor." (PMID 39843641, 2025). "Altogether, these findings align with our results, suggesting that CTTNBP2 and MCF2L may contribute to NB development and potentially exhibit tumor-suppressive roles." (PMID 39843641, 2025). "In this way, we observed that edited clones for both CTTNBP2 and MCF2L CREs led to reduced CTTNBP2 and MCF2L expression levels, respectively, increased cell proliferation and invasiveness, suggesting their role as tumor suppressor." (PMID 39843641, 2025).
CTTNBP2 also shares sentences with these, for which no sentence is quoted: infection (27 papers); viral infection (5); colon carcinoma (2); neurodevelopmental disorder (2); Acute hepatitis (1); Adenovirus infection (1); atherosclerosis (1); COVID-19 (1); Fulminant hepatic failure (1); Fulminant hepatitis (1); hepatoma (1); idiopathic osteonecrosis of the femoral head (1); juvenile idiopathic arthritis (1); latent infection (1); metabolic syndrome (1); oral cancer (1); respiratory infections (1); schizophrenia (1); Weaver syndrome (1).